TFEB (transcription factor EB)
Diseases named in the same sentence as TFEB in open-access papers (continued):
Sharing a sentence is not in itself a finding about the gene and the disease.
cancer (continued). "Based on the fact that both lysosomal function and autophagy are involved in cancer development, it is conceivable that TRPML1 may play an important role in TFEB-dependent pathway in cancer cells." (PMID 33419007, 2021). "Consistently, a high expression level of TFEB-mediated Wnt target genes, but not MCOLN1, was associated with poor prognosis in cancer patients." (PMID 33753903, 2021). "We showed that TFEB expression was increased in PCa tissues, and played a role in the progression of PCa by influencing ABCA2 activity in cancer-related lysosome biogenesis, which might contribute to patient’s poor clinical prognosis." (PMID 33732651, 2021). "Cellular TFEB, through activation of autolysosome flux and induction of CTSL, could induce ITGB1 degradation, which consequently suppressed the cancer cell migration." (PMID 33803301, 2021). "Of note, although TFEB and TFE3 seem to have a proapoptotic action upon treatment with etoposide, the overexpression of TFEB in cancer cells in the presence or absence of genotoxic agents appears to promote cell survival." (PMID 33490073, 2020). "In addition, a feedback loop has been proposed in which overexpression of TFEB, TFE3, or MITF upregulates RagD GTPase resulting in hyperactivation of mTORC1, induction of cellular proliferation, and cancer growth." (PMID 33490073, 2020). "Thus, Myc/Max and other bHLH transcription factors likely influence the effects of TFEB, MiTF and TFE3 to drive endolysosomal biogenesis in certain cancers." (PMID 31526156, 2019). "Some of the shared genomic features, such as gene fusions involving TFE3 or TFEB, are present in approximately 10% of samples and show no particular disposition to type I or type II cancers." (PMID 30099580, 2018). "While the oncogenic function of TRPML1, the main driver of TFEB activation in healthy cells, remains obscure, TPC1 and TPC2 are standing out as crucial drivers of many cancer hallmarks, including excessive proliferation, aberrant migration and sustained vascularization." (PMID 30591696, 2018). "The contribution of TFEB and TFE3 to cancer is probably complex and context dependent." (PMID 30520728, 2018). "Notably, siRNA-mediated downregulation of TFEB reduced survival of resistant cancer diapause-like cells by almost 50%, but did not affect survival of proliferating cancer cells." (PMID 40588651, 2025). "Notably, TFEB was found to be enriched in mitochondrial fraction and was not specific to cancer cell lines, as we also detected TFEB in the mitochondrial fraction of primary human monocyte derived macrophages." (PMID 38263327, 2024). "The orchestrated regulation of the autophagy–lysosomal system by TFEB/ZKSCAN3 highlight the importance of this pathway in cellular adaptation to environmental cues, which might be altered in pathological settings such as cancer." (PMID 30979895, 2019). "Thus, our study suggests that TFEB maintains intracellular amino acid availability without affecting bulk internalization of extracellular proteins, allowing cancer cells to proliferate even under nutrient deprivation." (PMID 30400219, 2018). "While some preclinical studies highlight potential negative effects of TFEB in cancer, it is important to note that its regulatory mechanism is not consistent across all cancer types, and may vary even between subtypes of the same cancer." (PMID 40083935, 2025). "At gene level, Beclin-1, p-62, BNIP3, NIX/BNIP3L and TFEB mRNAs were not significantly modulated, while LC3B and PINK1 mRNA levels were increased and decreased, respectively, in cachectic cancer patients." (PMID 27459917, 2016). "The molecular circuitry TFEB/SREPB2/cholesterol homeostasis genes is not cell type or cancer type-specific: indeed, THP-1 macrophages exposed to reactive oxygen species had increased nuclear translocation of TFEB, increased endogenous synthesis of cholesterol and efflux via ABCA1." (PMID 39107857, 2024).
cancer (continued). "Our results showed that TFEB does not affect macropinocytic uptake, but is responsible for lysosomal catabolism of internalized protein and maintenance of intracellular amino acid availability in KRAS-mutant cancer cells." (PMID 30400219, 2018). "In our practice work, increased TFEB gene copies were also found in low-grade eosinophilic unclassified RCC (not shown in the data), so we proposed it may represent chromosome 6 polysomy, which is nonspecific and seen in a variety of cancers." (PMID 36830782, 2023).
neurodegenerative disease (82 papers, 2015 to 2026). A disorder of the central nervous system characterized by gradual and progressive loss of neural tissue and neurologic function. "Impaired autophagy-lysosomal functions due to defective TFEB activity have been implicated in the pathogenesis of multiple neurodegenerative diseases." (PMID 41596551, 2026). "Further exploration of the start of this host-immune pathway will be important as TFEB has been implicated in human neurodegenerative diseases and is a therapeutic target for multiple neurodegenerative diseases." (PMID 40655012, 2025). "TFEB deficiency is also commonly observed in neurodegenerative diseases, leading to the accumulation of toxic proteins and dysfunctional organelles." (PMID 40430519, 2025). "We also examined the expression of transcription factor EB (TFEB), the main regulator of autophagy and lysosomal biogenesis, which has been implicated in the pathogenesis of neurodegenerative diseases." (PMID 37834028, 2023). "TFEB dysregulation is associated with neurodegenerative diseases and TFEB overexpression promotes neuroprotection." (PMID 33800981, 2021). "In terms of neurodegenerative diseases, the accumulation of pathogenic proteins can be alleviated by enhancing TFEB activity due to strong capacity in improving lysosomal function." (PMID 34490237, 2021). "Studies have revealed that TFEB is implicated in the pathogenesis of many neurodegenerative diseases." (PMID 34970136, 2021). "In humans, TFEB is the homolog of Drosophila Mitf that is best characterized for its role in autophagy and has been implicated in neurodegenerative disease." (PMID 33300868, 2020). "As for neurodegenerative diseases, TFEB regulates lysosomal exocytosis of tau and its loss of function exacerbates tau pathology and spreading in disorders characterized by tau accumulation, such as Alzheimer’s disease." (PMID 33316913, 2020). "Emerging evidence pointed out that defective activation of TFEB probably underlies aberrant lysosomal function failing to degrade aggregated toxic proteins in prevalent neurodegenerative diseases." (PMID 27209302, 2016). "TFEB is a master transcriptional regulator of autophagy and lysosome biogenesis that promotes intracellular clearance of pathogenic factors in many diseases including neurodegenerative diseases." (PMID 39454957, 2024). "Some protein aggregates associated with neurodegenerative diseases reportedly interact with TFEB." (PMID 36184826, 2023). "Secondly, TFEB is also activated by various stressors such as nutrient deficiency, oxidative stress, ER stress, and lysosomal stress, which have been considered as considered risk factors for neurodegenerative diseases." (PMID 36184826, 2023). "Indeed, some of the neurodegenerative disease-associated proteins have been shown to directly interfere with TFEB’s transactivation activity by affecting both its nuclear translocation and actions in the nucleus." (PMID 31297061, 2019). "However, it seems to be in conflict with the fact that proteasome impairment along with the deficiency of TFEB/ALP in neurodegenerative diseases." (PMID 31508418, 2019). "Recently, dysfunctional TFEB nuclear translocation was reported to induce deficient lysosomal capacity and autophagy arrest, which are associated with the development of HD, PD, AD and other neurodegenerative diseases." (PMID 30706760, 2019). "The highly conserved transcription factor EB (TFEB) is a master regulator of lysosomal biogenesis and autophagy, and has been shown to facilitate the degradation of toxic proteins associated with neurodegenerative diseases in mammalian disease models, and in flies." (PMID 37733679, 2023). "Given the critical role of lysosomal function in neurodegenerative diseases, we sought to identify novel, blood–brain-barrier-permeable small molecules that activate TFEB and promote lysosomal biogenesis." (PMID 41596551, 2026).
neurodegenerative disease (continued). "In several neurodegenerative disease models, TFEB plays a key role in enhancing autophagy, thereby alleviating disease progression." (PMID 39940940, 2025). "In models of ALS, fluvoxamine has also been shown to stabilize proteins like nucleoporin Pom121, which facilitates the translocation of TFEB, enhancing autophagy and lysosomal function, which is crucial in the pathology of most of neurodegenerative diseases." (PMID 40430519, 2025). "We then discuss the roles of TFEB and autophagy-lysosome pathways in major neurodegenerative diseases including AD and PD." (PMID 37191408, 2023). "TFEB function is perturbed across many neurodegenerative diseases and TFEB overexpression studies have suggested it to be a promising therapeutic target to prevent neuronal loss." (PMID 35786165, 2023). "This review mainly summarize the regulatory mechanism of TFEB and its function in neurodegenerative diseases." (PMID 36184826, 2023). "Several studies have shown that genetic and pharmacological modulation of TFEB are increasingly important strategies for the prevention and treatment of neurodegenerative diseases." (PMID 36184826, 2023). "As a master regulator of ALP pathways, TFEB has become an attractive target for alleviating ALP dysfunction in neurodegenerative diseases." (PMID 36184826, 2023). "Considerable attention is being paid to upregulating TFEB-induced lysosome biogenesis in the brain, where accumulation of abnormal proteins and lipids plays a role in multiple neurodegenerative diseases." (PMID 37548963, 2023). "Dysfunctions of TFEB and its role in the pathogenesis of several neurodegenerative diseases are reviewed." (PMID 36184826, 2023). "This is consistent with several studies of TFEB in the elimination of accumulated mutant proteins in neurodegenerative diseases." (PMID 35851059, 2022). "As such, TFEB dysfunction is associated with the pathogenesis of many neurodegenerative diseases, including AD, PD, HD, and SCA3, and TFEB overexpression can halt their progression." (PMID 35851059, 2022). "We conclude that the VPS41 variants specifically abrogate HOPS function, which interferes with the TFEB/TFE3 axis of mTORC1 signaling, and cause a neurodegenerative disease." (PMID 33851776, 2021). "TFEB overexpression has been proved to ameliorate the progression of neurodegenerative diseases, including PD, HD, and AD, as well as other tauopathy diseases." (PMID 34970136, 2021). "Owing to its involvement in cellular clearance pathways, TFEB is an appealing therapeutic target for neurodegenerative diseases, including AD and PD." (PMID 34702966, 2021). "TFEB, a member of the MiTF/TFE family, has received considerable attention and its dysfunction has been implicated in the pathogenesis of several neurodegenerative diseases." (PMID 34912803, 2021). "The discovery of transcription factor EB (TFEB) has triggered more and more studies that try to explore the therapeutic potential of targeting TFEB to treat neurodegenerative diseases, because it works as a master regulator of autophagy." (PMID 34930303, 2021). "In line with this, inefficient activation of TFEB has been suggested to potentially worsen neurodegenerative diseases by increasing the aggregate formation." (PMID 32374203, 2021). "Although the protective effect of p38 inhibition and its implication in neurodegenerative diseases are emerging, the mechanisms by which p38 regulates TFEB-mediated autophagy and inflammatory responses in microglia remain elusive." (PMID 34930303, 2021). "Given its molecular function, it seems that the expression and molecular activity of small TFEB are critical for the function of TFEB in vivo, and in the etiology of neurodegenerative diseases." (PMID 34702966, 2021). "By activating TFEB, E4 promoted autophagy flux and lysosomal biogenesis, which are essential for the clearance of protein aggregates, as seen in neurodegenerative diseases, including PD." (PMID 32098449, 2020).
neurodegenerative disease (continued). "Overall, the TFEB activator E4 deserves further study in animal models of neurodegenerative diseases, including PD." (PMID 32098449, 2020). "TFEB (transcription factor EB), an important molecule that regulates lysosomal and autophagy function, is regarded as a potential target for treating some neurodegenerative diseases." (PMID 30706760, 2019). "The impairment of proteasome function is well documented in neurodegenerative diseases, while both the activation of TFEB/ALP and inactivation of TFEB/ALP has been reported in neurodegenerative diseases." (PMID 31508418, 2019). "Recently, 14-3-3 proteins recognized phosphorylated transcription factor EB (TFEB) and affected the autophagy, which is strongly correlated with neurodegenerative disease." (PMID 31323761, 2019). "As increasing evidence demonstrates the beneficial effect of TFEB activation on promoting autophagy in neurodegenerative diseases, researchers have been prompted to identify molecules able to specifically activate TFEB as promising therapeutic tools." (PMID 30889901, 2019). "Our identification of an mTORC1-independent route to pharmacologically activate TFEB offers a new avenue to test TFEB-mediated enhancement of cellular clearance in neurodegenerative diseases." (PMID 28165011, 2017). "Even though the mechanisms behind TFEB accumulation in the Golgi apparatus are still unknown, the mislocalization of TFEB in the Golgi apparatus could be a common trait of different neurodegenerative diseases." (PMID 40243477, 2025). "Furthermore, TFEB activation as a therapeutic strategy for NDs has recently received attention, with several molecules being tested on neurodegenerative disease models." (PMID 40362383, 2025). "A series of studies revealed that activation of TFEB function is essential to prevent the progression of several prominent diseases, including neurodegenerative diseases and metabolic disorders, and these findings have attracted much attention to the mechanisms of TFEB regulation." (PMID 40880129, 2025). "Similarly, the activation of TFEB-mediated autophagy presents a promising strategy to clear pathological protein aggregates in neurodegenerative diseases." (PMID 40546257, 2025). "Abnormal activation of TFEB leads to dysfunction of ALP pathway in neurodegenerative diseases." (PMID 36184826, 2023). "This underscores the therapeutic potential of TFEB in the context of neurodegenerative diseases." (PMID 37143104, 2023). "The aim of this review is to summarize the current knowledge of TFEB-mediated lysosomal biogenesis and autophagy in NDs such as AD and PD, providing novel insight into understanding the pathogenesis of neurodegenerative diseases and the therapeutic potential of TFEB activators." (PMID 37191408, 2023). "Furthermore, we provide a description of the mechanism of TFEB activation and the implication of impaired TFEB signaling in neurodegenerative diseases." (PMID 36184826, 2023). "Finally, the potential therapeutic modulators of TFEB and their applications in neurodegenerative diseases are highlighted." (PMID 36184826, 2023). "Increasing the astrocytic or microglial clearance capacity through TFEB upregulation may represent a promising therapeutic strategy for neurodegenerative diseases." (PMID 35665902, 2022). "In recent years, several compounds able to modulate TFEB activity have been found to enhance autophagy and lysosomal biogenesis and might have therapeutic potential for the treatment of neurodegenerative diseases and LSD." (PMID 35665902, 2022). "Finally, the activation of MiTF/TFE transcription factors, particularly of TFEB, can promote the clearance of intracellular waste in both LSDs and more common neurodegenerative diseases." (PMID 35665902, 2022). "Indeed, trehalose, a natural disaccharide and TFEB activator, has been shown to promote autophagy by activating TFEB and ameliorating disease phenotypes in multiple neurodegenerative disease models." (PMID 35625599, 2022).